CSF1 (colony stimulating factor 1)
Diseases named in the same sentence as CSF1 in open-access papers (continued):
Sharing a sentence is not in itself a finding about the gene and the disease.
breast tumor (19 papers, 2013 to 2025). "The Ras/MAPK transcriptional signature was highly associated with expression of CXCL1/2/8 and CSF1/2/3 across TNBC/basal-like breast tumors, while T cell–recruiting CXCR3 chemokines were negatively associated with Ras/MAPK activity." (PMID 32634121, 2020). "The Pollard group observed that silencing of CSF-1 specifically in breast tumor cells decreases lung metastases as well as macrophage recruitment to the primary tumor." (PMID 40646332, 2025). "In breast tumors, macrophages are attracted by colony-stimulating factor-1 (CSF-1) released by cancer cells." (PMID 38787372, 2024). "In vivo invasion assays have shown that TAMs co-migrate with breast tumor cells and contribute to tumor cell invasion through a paracrine loop involving epidermal growth factor, produced by macrophages, and CSF-1 produced by cancer cells." (PMID 24019914, 2013). "We first determined whether CSF-1 levels are increased in TMEM doorway tumor cells at active TMEM doorways by multiplex staining of breast tumor tissue sections obtained from the polyoma middle T antigen (PyMT) mice injected i.v." (PMID 40646332, 2025). "Analyses of BM cells activated either by CSF-1/TLR4 ligands in vitro or orthotopic breast tumors in vivo showed expansion of stem/progenitor population and coincident upregulation of markers for at least four lineages including M2-macrophage, lymphatic endothelial, erythroid, and T-cells." (PMID 38640116, 2024). "miR-21 is reported to elevate CSF-1 secretion through PTEN downregulation and Akt phosphorylation in breast tumors." (PMID 32321589, 2020). "In mice bearing xenografted MCF-7 breast tumors, a PEG-conjugated anti-CSF-1 Fab was reported to have therapeutic effect, reducing macrophage recruitment to the tumor and reversing tumor resistance to combined chemotherapy." (PMID 24019914, 2013). "IL1B, IL6, TNF, IL8 and CXCR4 mRNA levels were significantly increased in the high AHR-expressing ERα-negative breast tumor subpopulation, while these associations were only observed for IL6 and CSF1 in the ERα-positive tumor subgroup." (PMID 29320557, 2018). "It has been published that STAT1 binds to Csf1 promoter in tumor cells; by this way STAT1 could regulate breast tumor-derived CSF-1 production which drives to the recruitment, in situ proliferation, and M2 phenotype of CD11blow F4/80high TAMs." (PMID 28197019, 2017). "Mechanistically, NCOA1 has been shown to up-regulate Twist1, ITGA5, CSF-1, SDF1 and CXCR4 expression, which are partially responsible for promoting metastasis through potentiating breast tumor cell epithelial-mesenchymal transition (EMT), migration, invasion and macrophage recruitment." (PMID 26287601, 2015).
colon carcinoma (19 papers, 2002 to 2025). "It is found that CSF1 overexpression in colon cancer cells is associated with macrophage infiltration, and colon cell-derived CSF1 promotes macrophage recruitment and increases IL-8 production bynbsp;macrophages." (PMID 33224886, 2020). "TAMs are recruited by various cytokines and chemokines secreted by cancer cells, such as monocyte chemotactic protein 1 (Mcp-1) and colony stimulating factor-1 (CSF-1) and are often the main cause of poor prognosis in multiple types of tumor such as colon cancer." (PMID 34948224, 2021). "Another recent study investigating breast and colon carcinoma models found that CSF-1/CSF-1R signaling inhibition stimulated the expansion of neo-epitope-specific T cells and promoted the development of an immune-permissive TME." (PMID 40646332, 2025). "Previous studies found overexpression of the CSF1 protein exclusively in colon cancer cells, which correlated with macrophage infiltration." (PMID 36433652, 2022). "MiR-150 is strongly generated in HEK 293T-derived exosomes, peripheral blood of tumor individuals, colony-stimulating factor 1 (CSF-1)-derived MQs of bone marrow as the serum of colon cancer cases." (PMID 33794771, 2021). "Studies have found that CSF1 derived from colon cancer cells can promote the recruitment of macrophages and polarization of TAMs." (PMID 33465115, 2021). "In a co-culture experiment of colon cancer cells with macrophages, it was shown that a high amount of co-cultured macrophages induced higher levels of CSF-1 expression and that high CSF-1 levels recruited higher numbers of macrophages vice versa." (PMID 32987848, 2020). "Our findings indicate that CT26 colon cancer cells secrete CSF-1 which serves as strong RAW 264.7 macrophage chemoattractant." (PMID 19696929, 2009). "Our study used a multiapproach perspective to understand further the immune effects, anti-tumor responses, and molecular mechanisms that might be involved in CSF1 blockade in murine breast and colon tumor models." (PMID 37505292, 2023). "Additionally, this study showed that increased CSF-1 levels in colon cancer cells decreased the expression of pro-inflammatory markers in macrophages." (PMID 32987848, 2020). "To assess the role of tumor-derived CSF1, we developed CRISPR-Cas9 knockouts in both the 4T1 mammary and MC38 colon carcinoma cell lines." (PMID 37505292, 2023). "Overall, this study provides a more complete understanding of the potential benefit of antagonizing the CSF1/CSF1R pathway in combination with therapeutic cancer vaccines in breast and colon carcinoma models." (PMID 37505292, 2023). "Cytokines such as CSF1 can activate RTK (CSF1R) and downstream STAT3 pathway, which can promote tumor migration and invasion in colon cancers." (PMID 35366939, 2022). "To explore the role of senescent tumor cells in macrophage polarization, we cocultured isolated primary monocytes with colon cancer cells (SW480), ROS induced senescent tumor cells (SW480/ROS), CXCL12, and/or CSF1 overexpressing cells." (PMID 33643790, 2021). "In this study, we developed and characterized CSF1 CRISPR-Cas9 knockouts in the 4T1 mammary and MC38 murine colon carcinoma cell lines to further understand the effects of CSF1 depletion in vitro and in vivo and determined its impact in tumor growth, tumor microenvironment, and epitope spreading." (PMID 37505292, 2023).
Alzheimer disease (18 papers, 2013 to 2025). A progressive, neurodegenerative disease characterized by loss of function and death of nerve cells in several areas of the brain leading to loss of cognitive function such as memory and language. "Further, IL34 expression levels are decreased (while CSF1 levels are increased) in Alzheimer’s disease and in animal models, and IL34 infusion is sufficient to rescue associative learning deficits in APP/PS1 mice." (PMID 38766127, 2025). "Microglial proliferation can be induced by systemic delivery or direct injection of CSF1 into the hippocampus of mouse models used to investigate prion disease, Alzheimer’s disease, ischemic stroke, and amyotrophic lateral sclerosis." (PMID 31554150, 2019). "Csf1r, which was downregulated in our screen, facilitates protection and survival of uninjured neurons in the hippocampus and cortex, and Csf1r signaling via administration of Csf1 ameliorates memory deficits in an Alzheimer's disease mouse model." (PMID 30013462, 2018). "Our findings suggest that CSF1, which has been a target of interest for cancers, Alzheimer’s disease, and other disorders, may be a novel target to alleviate negative affect during withdrawal from chronic alcohol exposure contributing to relapse-like behavior." (PMID 35668157, 2022). "Therefore, CSF1 is involved in the immune and inflammatory responses of various CNS diseases, including experimental autoimmune encephalomyelitis, Alzheimer's disease (AD), Parkinson's disease, and stroke." (PMID 33101590, 2020). "To approach this question, we also sought to identify differences between IL-34, CSF-1, and CSF-1R expression in human brain samples to establish whether there was an imbalance in Alzheimer's disease (AD)." (PMID 28848420, 2017). "Plasma Csf1 level increased in Alzheimer’s disease patients." (PMID 26696825, 2015).
leukemia (17 papers, 2014 to 2025). A malignant (clonal) hematologic disorder, involving hematopoietic stem cells and characterized by the presence of primitive or atypical myeloid or lymphoid cells in the bone marrow and the blood. "Our results indicate that leukemia therapies should not only target blasts but also their microenvironment and specifically macrophages and their receptor for CSF1." (PMID 34771453, 2021). "Opg mRNA was undetectable in the leukemia cells and controls, and Csf1 mRNA expression in leukemia cells was similar to controls." (PMID 29740160, 2018). "To gain insight into the mechanism of osteoclast-mediated bone resorption, we evaluated mRNA expression of Rankl (Tnfsf11), M-CSF (Csf1), and Opg in leukemia cells." (PMID 29740160, 2018). "Importantly, clinical trials using high dose CSF1 in leukaemias, including acute myeloid leukaemia, did not impact relapse rate." (PMID 33402221, 2021). "Moreover, CLL could induce polarization of M2 macrophages via the colony-stimulating factor-1 (CSF1)-CSF1R pathway, and blocking CSF1R signal transduction can reduce the leukemia cell load." (PMID 33553181, 2021). "Mechanistically, we recorded high levels of Rankl mRNA but not Csf1 mRNA in leukemia cells." (PMID 29740160, 2018).
lymphoma (16 papers, 2007 to 2025). A malignant (clonal) proliferation of B- lymphocytes or T- lymphocytes which involves the lymph nodes, bone marrow and/or extranodal sites. "As an additional important cytokine in this context, we suggest the RTK ligand CSF-1 that is essential for the development of lymphoma-associated macrophages." (PMID 32899476, 2020). "Indeed, our results clearly demonstrate the increased expression of CSF-1 in epithelial cells, while the expression of its receptor is found on the lymphoma cells." (PMID 35326399, 2022). "Finally, while the growth factor CSF-1 is highly expressed in the epithelial compartment, the expression of its specific receptor is noticeable in the lymphomas." (PMID 35326399, 2022). "Recently, an interplay between M2-macrophages and MCL cells was also described as relevant for the production of CSF1 and survival of lymphoma cells, which might explain the adverse prognostic role of the PCA detected in the present study." (PMID 33648463, 2021). "Mutation or loss of function may lead to abnormal activation of the notch signaling pathway, which further increases the expression of CCL2 and CSF1 and promotes the transformation of tumor-associated macrophages (TAM) to M2 phenotype, thus promoting lymphoma cell proliferation." (PMID 40589747, 2025). "Thus, we explored whether CSF-1 and its receptor are expressed in the epithelial or the lymphoma tissue compartments." (PMID 35326399, 2022). "Alternatively, we hypothesized that it may depend on CSF1/CSF1R pathway activation, as in solid cancers and lymphoma, which was confirmed by the abrogation of CD163 expression induced by AML CM supplemented with GW2580 or PLX3397." (PMID 34771453, 2021).
Sepsis (16 papers, 2014 to 2026). Sepsis is defined as life-threatening organ dysfunction caused by a dysregulated host response to infection. "Among these upregulated genes, prior research demonstrated that Nr4a2 has been linked to M2 polarization and protection in sepsis models, while Ccl17 and Csf1 are implicated in the recruitment of Th2 cells." (PMID 41026710, 2025). "Similarly, clearance functions of the macrophages of the liver are crucial to prevent sepsis in acute liver failure in humans, and CSF1-Fc rapidly promoted clearance functions in mouse disease models." (PMID 27445344, 2016). "CSF1 expression was not altered after LPS treatment of mice or of human FRCs, and it is attractive to speculate that FRCs promote macrophage polarization toward a regenerative and repair state, and away from an inflammatory state, as FRCs dampen innate immune‐driven inflammation in murine sepsis." (PMID 36991561, 2023).
Stroke (15 papers, 2013 to 2025). Sudden impairment of blood flow to a part of the brain due to occlusion or rupture of an artery to the brain. "Csf1 also promotes neural repair through neural stem cell proliferation and angiogenesis, though elevated Csf1 levels correlate with stroke risk, potentially via pathological vascular interactions." (PMID 41354822, 2025). "A subgroup of AD-MSCs expressing Csf1 emerged as a crucial functional component in stroke treatment." (PMID 40910104, 2025). "We observed marked differences between WT and CD36 KO of multiple well-described inflammatory players in neonatal stroke and hypoxia–ischemia, including down-regulation of Tlr4, Timp1, Csf-1 and CD68." (PMID 35148760, 2022). "Our findings echoed other studies showing that CSF1 reduced neuronal damage after stroke, experimental autoimmune encephalomyelitis, and AD." (PMID 33101590, 2020). "In addition, the marker genes of Cd11c microglial cells are highly expressed, including Spp1, Cst7, Csf1, and Lpl, which are microglial cells related to neurodegenerative diseases and stroke injuries." (PMID 37577391, 2023). "Consequently, enhancing the proportion of AD-MSCs expressing high levels of Csf1 may be pivotal in ensuring the therapeutic efficacy of stroke treatment products during their development." (PMID 40910104, 2025). "We found that the expression levels of some chemokines and cytokine receptors, such as CSF1R, CSF1, CCL3, CD4, and CCR2, were significantly different in ki20227-treated stroke mice compared to vehicle-treated stroke mice." (PMID 33177990, 2020). "The administration of the colony-stimulating factor 1 (CSF1, or macrophage colony-stimulating factor; M-CSF) receptor antagonist PLX3397 to a murine stroke model depletes microglia." (PMID 32967118, 2020).
Obesity (14 papers, 2016 to 2025). Accumulation of substantial excess body fat. "Obesity-associated signals such as CCL2, CSF1, and leptin not only increase macrophages infiltration but also direct their spatial recruitment to metabolically stressed or angiogenic regions of the tumor." (PMID 41310829, 2025). "TIRAP, TNFRSF1A, CASP1, CSF1, and ITGAM are associated with the development of type 2 diabetes, a condition linked to obesity." (PMID 39194753, 2024). "Levels of VEGFA and CSF-1 measured in cerebrospinal fluid have been found to be positively associated with BMI43 and the VEGFA gene is found to be mediating the connection between obesity and breast cancer." (PMID 33082373, 2020). "Though our observations confirmed a positive association with obesity, CSF1 did not perform well in discriminating ectopic fat depots." (PMID 30242179, 2018). "There, ATM produces MCP-1 and CSF-1 and accumulates both due to monocyte immigration from peripheral blood and proliferation of resident macrophages, which has specifically been brought into context of pro-inflammatory and atherosclerotic comorbidities of obesity." (PMID 35931812, 2022). "Thus, results suggest a low-grade inflammatory state in VEGFA, CSF-1 and CCL3 which is related to obesity and BMI." (PMID 33082373, 2020).
colorectal cancer (12 papers, 2013 to 2025). A primary or metastatic malignant neoplasm that affects the colon or rectum. "In colorectal cancer, an increase in the CD11b+F4/80hiMHCIIlow macrophage subpopulation was observed during cancer progression, as cancer cells release high amounts of CSF1, a crucial growth factor for macrophage proliferation and survival." (PMID 35163097, 2022).
gastric cancer (12 papers, 2014 to 2024). A primary or metastatic malignant neoplasm involving the stomach. "CSF1 was highly expressed in bile duct, brain, kidney, liver, and stomach cancers, while it was expressed at low levels in bladder, breast, colon, lung, pancreatic, prostate, and uterine cancers." (PMID 37097499, 2023). "Here we identified CSF1 was a direct target of miR-214 in gastric cancer through luciferase assays and further confirmed by western blot analysis." (PMID 24614175, 2014). "The CSF-1/CSF-1R axis may be a biomarker for the clinical diagnosis of lymph node and peritoneal metastasis of gastric cancer and is a potential therapeutic target for gastric cancer." (PMID 34729112, 2021). "Our data suggested that downregulation of miR-214 may facilitate the proliferation, migration and invasion capacity of gastric cancer cell through the CSF1-mediated signal pathway." (PMID 24614175, 2014). "And we identified that downregulation of microRNA-214 may regulate the proliferation, invasion and migration of gastric cancer cells by directly targeting CSF1." (PMID 24614175, 2014). "Studies have reported that elevated expression of CSF‐1/CSF‐1R significantly correlated with disease progression and with a poor overall survival (OS) and disease-free survival (DFS) of patients with gastric cancer." (PMID 34729112, 2021).
Hypertension (11 papers, 2012 to 2025). The presence of chronic increased pressure in the systemic arterial system. "Endothelial dysfunction, oxidative stress and inflammation associated with hypertension induced by Ang-II or DOCA/salt, are prevented in models deficient in macrophage colony stimulating factor (M-CSF or CSF-1) inducing decrease of monocyte/macrophage cell profile." (PMID 37854465, 2023). "We also included known hypertension-related genes, including AGTR1, NOS3, and CSF1." (PMID 27779208, 2016).
osteoarthritis (11 papers, 2010 to 2025). A noninflammatory degenerative joint disease occurring chiefly in older persons, characterized by degeneration of the articular cartilage, hypertrophy of bone at the margins and changes in the synovial membrane. "These cells showed enrichment for several immune modulators including Il1b, a key cytokine implicated in osteoarthritis pathogenies and Csf1, a key regulator of monocyte to macrophage differentiation." (PMID 39752388, 2025). "To understand whether IL34 and/or CSF1 have pathogenic roles in disease, we surveyed the expression of both in RA, osteoarthrosis (OA), and IBD." (PMID 31552020, 2019). "High positivity of CSF1 staining intensity was associated with an increased incidence of osteochondral lesions (bone erosion and osteoarthritis) (p = 0.009), but not with the rate of local recurrence." (PMID 25854167, 2015). "We hypothesized that, despite the histological similarity to GCTTS in arthrosis, the synovial metaplasia of capsules after implantation could cause GCTTS in the breast with the absence of CSF1 translocation." (PMID 35814458, 2022).
cervical cancer (10 papers, 2012 to 2024). A primary or metastatic malignant neoplasm involving the cervix. "TAMs seems to have a role in treatment resistance, as macrophage inhibitors (e.g. colony stimulating factor 1 (CSF-1) inhibitor) prior to chemotherapy have been shown to enhance the response to treatment in mammary and cervical cancer." (PMID 37182144, 2023). "Knockdown of CSF-1/CSF-1R increased apoptosis and reduced proliferation and migration of cervical cancer cells." (PMID 29228668, 2017).